NOTCH1 (notch receptor 1)
Diseases named in the same sentence as NOTCH1 in open-access papers (continued):
Sharing a sentence is not in itself a finding about the gene and the disease.
adenoid cystic carcinoma (16 papers, 2014 to 2025). A malignant tumor arising from the epithelial cells. "Most studies suggest that NOTCH1 alterations are associated with prognosis in adenoid cystic carcinoma (ACC), but findings remain fragmented." (PMID 40789681, 2025). "In turn, 12 patients with adenoid cystic carcinoma and confirmed activating NOTCH1 mutations were targeted with monoclonal antibody, brontictuzumab, and the phase I study resulted in an objective response rate (ORR) of 17%." (PMID 37439929, 2023). "Brontictuzumab is a Notch1 mAb, and its notable clinical benefits in Notch1-mutated adenoid cystic carcinoma (ACC) patients have been documented." (PMID 37853437, 2023). "In adenoid cystic carcinoma (ACC), mutations in the Notch1 gene which impair function correlate with higher metastatic rates and shorter survival periods." (PMID 38866828, 2024). "In an adenoid cystic carcinoma xenograft model with Notch1 mutations, the tumor volumes and body weight were reduced by AL101, which provided fairly broad therapeutic prospects in adenoid cystic carcinoma." (PMID 36646686, 2023). "The most common genetic aberrations among patients with adenoid cystic carcinoma (N = 49) were NOTCH1/2 (26.5% [13/49]) (mainly NOTCH1 (24.5% [12/49]) and KDM6A (26.5% [13/49])." (PMID 26247885, 2015). "Interestingly, the Notch-associated bHLH transcription factor HEY1 was also identified as a target DEG and showed the strongest downregulation amongst Notch signaling genes, despite being previously reported as a positively regulated NOTCH1 effector in adenoid cystic carcinoma cells." (PMID 38994994, 2024). "Similarly, in adenoid cystic carcinoma, mutations in NOTCH1 and NOTCH2 have been identified as altered targets in various genomic screenings, and knock-down of Notch1 or Notch2 inhibits proliferation of adenoid cystic carcinomas in models of the disease." (PMID 31455013, 2019). "NOTCH1 and truncated MYB—which together define a common subtype of adenoid cystic carcinoma —were also selected for the fly model, bringing the final number of modeled cancer drivers to six patient variants modeled by five targeted fly genes." (PMID 33733072, 2021). "Immunohistochemistry was used to detect the expression of NOTCH1 and HEY1 in 27 cases of the adenoid cystic carcinoma tissues." (PMID 32025208, 2020). "As another pivotal member of the NOTCH1 signaling path, we investigated the expression of HEY1 in salivary adenoid cystic carcinoma, including 77 samples of normal tissue and 87 adenoid cystic carcinoma cases, via immunohistochemistry." (PMID 32025208, 2020). "In addition, the expression of both Notch1 and FABP7 had important prognostic value in patients who underwent resection of tracheobronchial adenoid cystic carcinomas." (PMID 35783014, 2022). "Furthermore, the expression of NOTCH1 and HEY1 exhibited clearly positive correlation in adenoid cystic carcinoma tissues." (PMID 32025208, 2020). "In our previous study, we found that NOTCH1 was upregulated in the highly metastatic adenoid cystic carcinoma cell line, ACC-M, compared with the low metastatic cell line, ACC-2, suggesting that NOTCH1 contributes to the metastasis of adenoid cystic carcinoma." (PMID 25149541, 2014). "Likewise, adenoid cystic carcinoma (ACC) tumor xenografts with activating Notch1 mutations responded to Notch inhibition, whereas the tumors without Notch1 mutation and low levels of NICD1 were resistant." (PMID 26713603, 2016).
mantle cell lymphoma (16 papers, 2013 to 2024). Mantle cell lymphoma is a rare form of malignant non-Hodgkin lymphoma affecting B lymphocytes in the lymph nodes in a region called the ``mantle zone''. "NOTCH1 gene mutations in mantle cell lymphoma (MCL) have been described in about 5–10% of cases and are associated with significantly shorter survival rates." (PMID 31676012, 2019). "Similar NOTCH1 and NOTCH2 mutations have been seen in multiple B-cell malignancies including chronic lymphocytic leukaemia (CLL), mantle cell lymphoma (MCL), Hodgkin’s and Burkitt’s lymphomas, further supporting its role in these haematological malignancies." (PMID 32575680, 2020). "The capacity of NOTCH1 to induce MYC expression was also confirmed by later studies in CLL, mantle cell lymphoma (MCL) and other non-hematological cancers." (PMID 35740661, 2022).
aortic aneurysm (15 papers, 2013 to 2024). A ruptured aneurysm located in the wall of the proximal portion of the descending aorta proceeding from the arch of the aorta. "It is important to note that our patient also had a bicuspid aortic valve, and mutations in NOTCH1 have been associated with isolated and familial bicuspid aortic valve and aortic aneurysm." (PMID 36140728, 2022). "In this study, protein analyses of human aortic aneurysm tissues suggested the insufficient expression of NOTCH1 in BAV-TAA was associated with the impaired mitochondrial dynamics and OXPHOS." (PMID 34486519, 2021). "Ambitiously, in another multiple center sequencing study, NOTCH1 was suggested as a protective factor for BAV related aortic aneurysm." (PMID 34461831, 2021). "The results reveal a decrease in aortic aneurysm progression due to the presence of the Notch1 protein." (PMID 34677194, 2021). "Our findings support the argument that NOTCH1-dependent mechanism has a heterogeneity and low penetrance of aortic aneurysm in the BAV patient." (PMID 34461831, 2021). "We present evidence that myeloid-specific Notch1 haploinsufficiency protects against the formation of AAA, whereas SMC-specific Notch1 haploinsufficiency interferes with the progression of aortic aneurysms." (PMID 28562688, 2017). "The associations of NOTCH1 mutations with various cardiovascular phenotypes, such as BAV, aortic aneurysm, and aortic coarctation, have been reported earlier." (PMID 28246602, 2017). "Inhibition of Notch1-mediated inflammation prevented AAA via the PI3K/Akt signaling pathway, and AGE-RAGE stress was associated with the pathogenesis of aortic aneurysms." (PMID 36338468, 2022). "Based on this evidence, we deduced that metformin may protect hPSC-HASMCs by switching them to a contractile phenotype via NOTCH 1 to delay the progression of aortic aneurysm." (PMID 33816448, 2021). "Also, genetically modified mouse aortic aneurysm model is required to further elucidate the genetic mechanism of NOTCH1—mitofusin axis in ascending aortic aneurysm." (PMID 34486519, 2021). "Collectively, these findings imply that Notch1 signaling in different cell types affects the development of aortic aneurysm by multifarious mechanisms and represents a potential target to mitigate the deleterious effects of AAA at different stages of the disease progression." (PMID 28562688, 2017). "Thus, as the evidence in our study showed, we inferred that metformin prescription may be able to limit the progress of aortic aneurysm via NOTCH 1 signalling." (PMID 33816448, 2021). "Moreover, we found that the phenotypic switch may be related to the presence of NOTCH 1 signalling, showing the potential to serve as a therapeutic target in preventing the progression of aortic aneurysm." (PMID 33816448, 2021). "Although Notch1+/– mice are not reported to have a congenital cardiac phenotype, they are known to have impaired lipid metabolism and develop aortic aneurysms with age." (PMID 39437002, 2024). "Since we found that NOTCH1 and NOTCH3 levels are differentially expressed in the aortic aneurysm samples, we next evaluated if they might regulate PDE5 expression in VSMCs in vitro." (PMID 31434939, 2019).
congenital heart disease (15 papers, 2016 to 2026). A heart disease that is present at birth. "Pathogenic variants in NOTCH1 are associated with non-syndromic congenital heart disease (CHD) and Adams–Oliver syndrome (AOS)." (PMID 38778082, 2024). "NOTCH1 pathogenic variants have been associated not only with non-syndromic TAAs but also with conotruncal congenital heart defects and complex syndromes such as Adams–Oliver." (PMID 37239988, 2023). "The tertiary aim was a critical review of the available literature and an overview of the contribution of NOTCH1 variants in congenital heart disease." (PMID 35288444, 2022). "NOTCH1 is the most commonly associated gene for the congenital heart defect of tetralogy of Fallot, and the NOTCH1 de novo variant carrier had a diagnosis of APAH-CHD with tetralogy of Fallot." (PMID 33081265, 2020). "While both gain and loss of function mutations have been reported for NOTCH1, identification of families with multiple affected members carrying novel nonsense mutations remains rare in the context of congenital heart disease." (PMID 27760138, 2016). "Furthermore, several studies have suggested that NOTCH-1 mutation genes are among the most prevalent causes of Congenital Heart Disease (CHD)." (PMID 38808331, 2024). "Loss of function mutations in NOTCH1 (OMIM 190198) has previously been associated with congenital heart disease involving the aortic valve, left ventricle outflow tract, and mitral valve that segregates in affected pedigrees as an autosomal dominant trait with variable expressivity." (PMID 32720365, 2020). "The association with the genes NKX2-5, NOTCH1, GATA4, GATA6 and HAND1 links trabeculation to congenital heart disease (CHD)." (PMID 39567769, 2024). "Currently, many efforts are being made to understand the role of the NOTCH1 gene in congenital heart defects." (PMID 37239988, 2023). "A systematic literature search was performed in the NCBI PubMed database to identify publications reporting NOTCH1 sequencing in context of congenital heart disease." (PMID 35288444, 2022). "In this study, we present results of NOTCH1 sequencing of 8 pedigrees with familial BAV and 381 patients with sporadic BAV as well as results of a systematic review of NOTCH1 sequencing in 528 pedigrees with familial congenital cardiac lesions and 9449 sporadic cases of congenital heart disease." (PMID 35288444, 2022). "In mice with congenital heart disease, Notch1 is a target of miR-34a, suggesting that the miR-34a-mediated effect on HF development may be due to Notch1 inhibition." (PMID 34527667, 2021). "Even though no gross malformation was observed in adult Pdgfd-/- heart tissue, we found reduced mRNA expression of Gata4 and Notch1, two genes involved in cardiac development, maintenance of adult cardiac function and control of cell fate and differentiation, as well as in congenital heart disease." (PMID 27032083, 2016). "However, de novo deletions containing the NOTCH1 gene have only been described in patients with congenital heart defects such as tetralogy of Fallot (TOF), hypoplastic left heart syndrome (HLHS), and ventricular septal defect, but not in non-syndromic TAAs and tricuspid aortic valve (TAV)." (PMID 37239988, 2023).
thoracic aortic aneurysm (15 papers, 2013 to 2025). An aneurysm formed in the wall of the proximal portion of the descending aorta proceeding from the arch of the aorta. "Deleterious variants within NOTCH1 have been associated with bicuspid aortic valve disease, thoracic aortic aneurysms, and pulmonary hypertension." (PMID 37754822, 2023). "Otherwise, thoracic aortic aneurysms have also been described in pedigrees with inactivating NOTCH1 mutations." (PMID 34071740, 2021). "Finally, in another study, thoracic aortic aneurysms (TAA) have been described in six individuals with NOTCH1 variants, and these were associated with BAV in four and with severe aortic valve stenosis (AVS) in the other two cases." (PMID 37239988, 2023). "Relevant studies have shown that the formation of thoracic aortic aneurysm in some patients could be caused by Notch1 gene mutation affecting the SMC differentiation of bicuspid aortic valve." (PMID 35902792, 2022). "Exome sequencing in four members of a three‐generational family (three affected and one unaffected subject) with clinical phenotypes including aortic valve stenosis, thoracic aortic aneurysm, and ventricular septal defect revealed nonsense mutation (p.Tyr291*) in NOTCH1." (PMID 32720365, 2020). "Mutations in genes such as NOTCH1, GATA5, and ACTA2 have been implicated in the pathogenesis of both BAV and thoracic aortic aneurysms, suggesting shared genetic etiologies." (PMID 40110250, 2025). "Mutations in NOTCH1 are known to cause familial BAV disease, whereas mutations in MYH11 cause hereditary thoracic aortic aneurysms." (PMID 35711915, 2022). "Although two cases are not enough to draw a definitive and reliable conclusion, this study is an invitation to explore the NOTCH1 gene and the genes involved in its regulation as a new cause of thoracic aortic aneurysm in the absence of BAV." (PMID 37239988, 2023). "Moreover, the identification of notch receptor 1 gene pathogenic variant in a TAD patient with tricuspid aortic valve confirms that the alteration of this gene is a novel cause of thoracic aortic aneurysm alone and not as a result of the BAV, as recently reported in the literature." (PMID 41475307, 2025). "In the presence of bicuspid aortic valve, the demonstration of genetic alterations at the level of NOTCH-1 and SIRT-1 could suggest a strict monitoring of patients due to the higher likelihood to develop thoracic aortic aneurysm." (PMID 24453931, 2013).
Bicuspid aortic valve (14 papers, 2013 to 2024). The presence of an aortic valve with two instead of the normal three cusps (flaps). "Previous research suggested that pathogenic NOTCH1 mutations explain up to 5% of all bicuspid aortic valve (BAV) disease." (PMID 35288444, 2022). "Heterozygous Gata6 loss-of-function mutations alone or humanized Mib1 mutations in a NOTCH1-sensitized genetic background cause bicuspid aortic valve (BAV) and a membranous ventricular septal defect (VSD), consistent with MIB1 and NOTCH1 functioning in the same pathway." (PMID 39057643, 2024). "Bicuspid aortic valve (BAV) is associated with genetic defects (NOTCH 1, GATA 5) and aortopathy." (PMID 34300236, 2021). "Mutations in NOTCH1 have been linked to bicuspid aortic valve (BAV) and aortopathy in humans." (PMID 25914885, 2015). "Among these genes and pathways is the Notch1 signaling cascade, described in connection to congenital heart disorders, bicuspid aortic valve and aortic aneurhysma infamilial cases of congenital heart and valve malformations." (PMID 39057646, 2024). "Bicuspid aortic valve (BAV) is a congenital malformation affecting 1–2% of the population, associated with aortopathy and genetic defects such as NOTCH1 and GATA5 mutations." (PMID 34300236, 2021). "Congenital aortic valve malformations such as bicuspid aortic valve (BAV) underlie the majority of cases of calcific AVD, and can be caused by loss of function mutations in NOTCH1." (PMID 29552567, 2014). "The purpose of our study was to investigate the potential contribution of germline mutations in NOTCH1, GATA5 and TGFBR1 and TGFBR2 genes in a cohort of Italian patients with familial Bicuspid Aortic Valve (BAV)." (PMID 23578328, 2013). "They failed to identified causal variant in the patients and concluded that the NOTCH1 variant contributed little to the noncalcified bicuspid aortic valve combined with ascending aortic aneurysm." (PMID 34461831, 2021).
brain tumors (14 papers, 2012 to 2024). "Here, we targeted the IGF pathway using ceritinib, an off-target inhibitor of the IGF1 receptor (IGF1R) and insulin receptor (INSR), in a pediatric patient with an unclassified brain tumor and a notch receptor 1 (NOTCH1) germline mutation." (PMID 31480400, 2019). "Several studies during recent years reported dysregulated NOTCH signaling activity (NOTCH 1–4) in human brain tumors." (PMID 33926464, 2021). "MiRNA-146a-5p has been described as a native molecular brake for oncogenesis in aggressive and deadly brain tumours via NOTCH1 signalling." (PMID 33610185, 2021). "Secondary transplants of NOTCH1− cells were unable to generate new primary tumors when reinjected into mouse cerebella, contrasting with the NOTCH1+ cells which robustly formed brain tumors and spinal metastases upon reinjection." (PMID 30297829, 2018). "High-field MRI confirmed the brain tumor growth attenuation after NOTCH1 knockdown." (PMID 33579922, 2021). "Additionally, it has been shown that Notch-1 and Notch-2 exert opposite regulatory effects on the growth of embryonic brain tumors." (PMID 32993109, 2020).
glomerulosclerosis (14 papers, 2013 to 2025). A hardening of the kidney glomerulus caused by scarring of the blood vessels. "Aberrant activation of Notch1 signaling in glomerular endothelium induced severe albuminuria which was an independent risk factor of glomerulosclerosis." (PMID 35680856, 2022). "Given the differential role of Notch1 and 2, it is likely that the loss of Notch1 and maintenance of Notch 2 in podocytes has a superior effect on glomerulosclerosis and proteinuria than the podocyte-specific loss of the pan-Notch regulator Rbpjk." (PMID 33519447, 2020). "Consistent with previous findings, podocyte-specific expression of the active Notch1 intracellular domain caused albuminuria and glomerulosclerosis, while mice with overexpression of the Notch2 intracellular domain did not exhibit phenotypic alterations." (PMID 33519447, 2020). "In this context, the overexpression of active Notch1 in podocytes is not limited to DN but is a common type of intracellular signaling underlying glomerulopathy in several proteinuric kidney diseases, where it strongly correlates with glomerulosclerosis." (PMID 33519447, 2020). "A previous study reported that a cleaved Notch1 fragment expression in podocytes or glomeruli was correlated with albuminuria and glomerulosclerosis in various kidney disorders." (PMID 34823491, 2021). "De novo expression of active Notch1 in mature podocytes has been shown to induce apoptosis, which translates in vivo into the development of proteinuria and glomerulosclerosis." (PMID 33519447, 2020). "Notch1 may participate in the development of fibrosis, which is correlated with glomerular sclerosis." (PMID 23691527, 2013). "Notch pathway inhibitors were found to weaken glomerulosclerosis and RIF by decreasing the expression of Jagged1, Notch1, NICD1, HEY1, HES1α-SMA, and fibronectin in uremic rats." (PMID 36793762, 2023). "In accordance with these findings, inhibition of Notch1 pathway by blocking the release of NICD1 using γ-secretase inhibitor also alleviates albuminuria and glomerulosclerosis in rat DKD model." (PMID 28871126, 2017).